MICA (MHC class I polypeptide-related sequence A)
Diseases named in the same sentence as MICA in open-access papers (continued):
Sharing a sentence is not in itself a finding about the gene and the disease.
tumor (continued). "In a clinical trial of melanoma patients with anti-CTLA-4 antibody blockade vaccine with autologous tumor cells engineered to express GM-CSF, it was shown that patients with high level of anti-MICA autoantibody presented better response to therapy." (PMID 25788898, 2015). "This strong selection pressure seems to have led tumor cells to evolve mechanisms to minimize or avoid the response mediated by NKG2D by shedding MICA from the cell surface 30,31." (PMID 24403192, 2014). "Interaction of MICA on the surface of tumor cells with the chaperon molecule ERp5 plays a relevant role in sMICA shedding." (PMID 24711808, 2014). "The importance of ligands expression for tumor cell recognition by NK cells is a key factor for anti-tumor immune response, as illustrated by the strong prognostic value of MICA/MICB, RAET1G, and ULBP2 expression in colorectal cancer and breast cancer." (PMID 24715892, 2014). "The shedding of soluble MICA by human tumors not only hinders recognition of the MICA-expression tumor cells, but also results in systemic downregulation of NKG2D on NK and CD8+ T cells, and evasion of NKG2D-mediated immune recognition 30,31." (PMID 24403192, 2014). "Overexpression of mouse and human NKG2D ligands such as Rae-1, H60, MULT-1, and MICA on tumor cells resulted in a retarded tumor growth or tumor rejection due to NK-cell mediated cytolysis." (PMID 23776472, 2013). "Our present study and those of others showed that geftinib can partially up-regulate NKG2D ligands ULBP1, ULBP2 or MICA on tumor cells." (PMID 23937717, 2013). "This explains the capacities of NK cells to kill MGUS tumor cells by interaction between MICA and NKG2D." (PMID 24391641, 2013). "The HTB-186 tumor cell line expressed the highest levels of HLA class I, MICA, ULBP-2, ULBP-3 and the lowest NKG2DLs/HLA class I ratio." (PMID 23626949, 2013). "Previously, hypoxia has been shown to increase tumor cell secretion of MICA that, upon binding, provoked a decrease in NKG2D surface expression." (PMID 23724099, 2013). "In MGUS, tumor-cells express high levels of MICA, whereas low levels of sMICA are detected in peripheral blood." (PMID 24391641, 2013). "In this study, we analyzed tumor samples from 54 MB patients for expression of major histocompatibility complex class I-related chains A (MICA) and UL16 binding protein (ULPB-2), which are ligands for the NK group 2 member D activatory receptor (NKG2D)." (PMID 23626949, 2013). "Conversely, MM patients present high plasma level of sMICA while tumor-cells express low level of MICA, thus impending NK stimulation via NKG2D." (PMID 24391641, 2013). "The best known ligand of NKG2D is the HLA class I-related molecule MICA, which can be found surface-expressed on infected or tumor cells, but also has a circulating soluble form." (PMID 23638076, 2013). "In line with the flow cytometric data on infected cells, we readily detected expression of HLA-1 and MICA/B molecules in tumor cells." (PMID 22253598, 2012). "It was shown that azacytidine and decitabine alone or combined with other drugs induced expression of the NKG2DLs MICA/B or UL16-binding proteins (ULBP) on various tumor cell lines." (PMID 23316191, 2012). "Shedding of NKG2D ligands, in particular MICA, from the cell surface represents a mechanism by which tumours escape NKG2D immune surveillance." (PMID 22587892, 2012). "In the case for TSA, the mechanisms for this tumour cytotoxicity were associated with increased histone H3 acetylation and reduced HDAC1 expression at the MICA and MICB promoters regions." (PMID 22461998, 2012). "NKG2D, one of the best characterized NK cell activating receptors, can promote tumor lysis upon recognition of MICA, MICB or the ULBPs." (PMID 21631944, 2011). "Herein we show that the tumor cell survival from the recognition of γδ T cells is correlated with the down regulation of cell surface MICA levels and reduced expression of cell cycle related molecules, as well as up-regulation of Erk1/2 signaling." (PMID 21935360, 2011).
tumor (continued). "Gemcitabine therapy leads to increased serum MICA levels, probably as a result of increased MICA expression in tumor tissues." (PMID 21605422, 2011). "Mann-Whitney test revealed a p value of 0.018, indicating that serum MICA levels in patients who were eligible for tumor resecton is significantly lower than those with unresectable tumors." (PMID 21605422, 2011). "MICA is preserved in most mammals except for rodents and is present at high levels in gastrointestinal epithelium, and on tumor cells of epithelial origin." (PMID 21935360, 2011). "The NKG2D downregulation in cancer patients has been correlated with high levels of circulating MICA/B molecules shed by the tumor burden, or with circulating mature TGF-β or to regulatory T cells expressing membrane bound TGF-β." (PMID 19319200, 2009). "NKG2D plays an important role in the immune recognition of tumor targets after engagement by MICA molecules." (PMID 18208618, 2008). "Recent reports have revealed a new tumor evasion strategy involving MICA release from malignant cell surface in different human tumors." (PMID 18208618, 2008). "Nevertheless, we recommend prioritizing the use of PD-L1 antibodies over signaling inhibitors or cytokine-targeted therapies, as the latter could downregulate MICA/B, potentially compromising anti-tumor immunity." (PMID 40369131, 2025). "Tumor cells shed MICA and other NKG2D ligands through proteolysis to escape immune surveillance." (PMID 41301424, 2025). "It is tempting to speculate that high MICA/B production by the neoplastic HRS cells of cHL upon SFN treatment may promote anti-tumor immune responses through activation of the NK and CD8+ T- and NK cells in the TME resulting in tumor cell killing." (PMID 40295827, 2025). "Binding to respective tumor cell-associated antigen (TAA) was assessed by incubating supernatants containing BICA on EGFR/MICA-positive or -negative cell lines." (PMID 40741595, 2025). "Furthermore, CHMP2A has been shown to induce apoptosis in NK cells, thereby reducing their anti-tumor activity through the secretion of EVs expressing MICA/B and TRAIL." (PMID 40149859, 2025). "Authors showed that silencing MALAT1 or ADAM10 could prevent MICA/B release, enhancing NK cell-mediated clearance of senescent tumor cells." (PMID 40496868, 2025). "It is hypothesized that the stabilization of MICA/B at the tumor cell surface not only prevents immune evasion through MICA/B shedding but also increases the target antigen density to enhance ADCC and antibody-dependent cellular phagocytosis." (PMID 40116579, 2025). "Importantly, a variety of approaches can be considered to enhance NK cell-mediated tumor immunity in preinvasive disease, including antibodies that block inhibitory receptors (NKG2A) or to prevent MICA/B proteolytic shedding by tumor cells." (PMID 39803458, 2025). "Therefore, assessment of plasma MICA/B is an important marker for evaluating the tumor immune response of the patients." (PMID 40108523, 2025). "The IFN-γ pathway was activated in MICA+ tumor cells and MMP9+ macrophages." (PMID 38254761, 2024). "Conversely, matrix metalloproteinases (MMPs) and a disintegrin and metalloproteinases (ADAMs) secreted by tumor cells or non-cancerous cells within the TME have been implicated in the proteolytic shedding of MICA." (PMID 38254761, 2024). "To further validate the involvement of the PROS1-AXL axis in the upregulation of macrophage MMP9 via MICA+ tumor cells, we introduced the AXL inhibitor cabozantinib to macrophages stimulated via recombinant human PROS1 protein and co-cultured with IRF1+ Huh7 cells." (PMID 38254761, 2024). "By overexpressing ADAM proteases, tumor cells shed MICA, avoiding NK cell activation." (PMID 38180524, 2024). "Understanding the mechanisms by which DHT influences MICA expression and the subsequent immune response in the context of EBVaGC can provide valuable insights into potential therapeutic strategies for enhancing anti-tumor immunity." (PMID 39335190, 2024).
tumor (continued). "MICA/B and sMICA/B, which represent the biological behavior centered on cancer cells and the state of tumor immune surveillance, may have predictive value for cancer patients." (PMID 38882209, 2024). "Consequently, the released soluble MICA (sMICA) played a pivotal role in promoting tumor immune evasion." (PMID 38254761, 2024). "Finally, we observed that MMP9 secreted by macrophages hydrolyzed MICA, leading to the release of sMICA and promoted immune evasion by the tumor." (PMID 38254761, 2024). "The nanobody-DM1 conjugate selectively kills MICA positive tumor cells in vitro." (PMID 38550583, 2024). "MICA belongs to the non-classical class I family with highly polymorphic human stress antigens associated with tumor and inflammation surveillance." (PMID 38474281, 2024). "Notably, we observed the presence of L-R interactions involving PROS1-AXL and CCL15-CCR1 between MICA+ tumor cells and MMP9+ macrophages." (PMID 38254761, 2024). "However, cancer cells can cleave MICA, making it soluble and de-targeting tumor cells from NK cells, leading to tumor immune escape." (PMID 38180524, 2024). "NKG2D is the most typical activating receptor on NK cells with the ability to recognize the structural analogs of MHC-I like ULBP and MICA/B, which can be upregulated through infection, stress, and tumor cells, and plays a critical role in processing tumor immune surveillance." (PMID 39065636, 2024). "Moreover, scRNA-seq analyses revealed a significant increase in PROS1 expression in HCC tumor cells exhibiting positive expression of IRF1 or MICA." (PMID 38254761, 2024). "Finally, OAdv-MICA overexpression in immunocompetent tumor-bearing mice elicits tumor-specific immune response resulting in a greater tumor growth control." (PMID 38180524, 2024). "In tumor immunity, HSF1 inhibition triggers loss of NK cell activation ligand MICA/B." (PMID 38743344, 2024). "However, the shedding of MICA and the prolonged exposure to the soluble MICA (sMICA) environment lead to desensitization and dysfunctional of NK cells, becoming a crucial therapeutic target in tumor immune evasion." (PMID 39048814, 2024). "Finally, we observed that MMP9 secreted by macrophages hydrolyzed MICA, leading to the release of sMICA and promoting immune evasion by the tumor." (PMID 38254761, 2024). "Furthermore, the proteolytic cleavage of MICA by adisintegrin metalloproteinase domains (ADAMs) and tumour secreted metalloproteases (MMPs) or secretion in exosomes is the underlying mechanism." (PMID 37784183, 2023). "Upon the recognition of tumor cells, NK-cell activation occurs through the interaction of NKG2D receptors on the surface of NK cells with ULBP ligands and the MHC class I chain-associated proteins MICA and MICB on the surface of tumor cells." (PMID 36766706, 2023). "MICA is a well-known ligand present on tumor cells that binds the receptor NKG2D on NK cells." (PMID 38213954, 2023). "The binding of MICA/B on tumor cells and NKG2D on NK cells activates NK cells." (PMID 38022646, 2023). "Therefore, previous research has found that higher concentrations of soluble MICA (sMICA) and sMICB molecules in serum play a critical role in tumor evolution and poor prognosis through an immune evasion mechanism." (PMID 38033491, 2023). "In addition, IMiDs make tumor cells more susceptible to NK cell killing by upregulating ligands for NKG2D, DNAM1, MICA, and PVR in tumor cells." (PMID 37539051, 2023). "Moreover, high TMEM201 levels were significantly correlated with increased MICA expression, which plays a role in tumor-immune-escape mechanisms." (PMID 37373430, 2023). "Moreover, in patients with pancreatic cancer who received neoadjuvant gemcitabine, MICA was expressed on 85% of tumours, in contrast to 36% of cases in the placebo-treated control group." (PMID 37626965, 2023). "Furthermore, tumor cell lines treated with Bix-01294, a G9a inhibitor, also showed upregulation of MICA and MICB activating ligands." (PMID 37090711, 2023).
tumor (continued). "Concerning sensitization of tumor cells, Poggi and collaborators showed that trans-retinoic acid, an active metabolite of vitamin A, was able to induce MICA expression at the surface of CLL cells from patients, leading to an increase of their lysis by autologous Vδ1 T cells." (PMID 37426670, 2023). "This difference might be associated with the expression of MICA/B, UL-16 binding protein (ULBP), intercellular adhesion molecule (ICAM-1), and PVR on the surface of tumor cells." (PMID 37597083, 2023). "As we expected, IRF1 positive expression in tumor cells was consistent with MICA positive." (PMID 36765808, 2023). "Furthermore, preserving the anti-tumour activity of T cells and NK cells in MHC-I deficient tumours is achievable through a vaccine approach that targets MICA and MICB stress proteins." (PMID 37454231, 2023). "Similarly, NK cell-tumor cell-interaction is disturbed since expression of NKG2D is downregulated by soluble MICA and MICB released from adjacent tumor cells." (PMID 37684704, 2023). "At the same time, the expression levels of MICA on the tumour cell surface may determine anti-tumour efficacy, while those shed in the serum may act as a decoy of NKG2D to avoid immune rejection." (PMID 37784183, 2023). "However, tumor cells are able to evade recognition by NKG2D-expressing NK cells by shedding the MICA/B ligand from their surface and allowing them to continue to grow and metastasize." (PMID 36830840, 2023). "Therefore, a novel therapeutic strategy being tested in animal tumour models is to use antibodies targeting the proteolytic cleavage site to prevent MICA/B release and reduce cancer spread." (PMID 36980527, 2023). "An additional gene copy of MICA may result in higher levels of membrane-bound MICA and may therefore be beneficial for the recognition of tumor cells by the immune system." (PMID 38035108, 2023). "Besides KLF4 we also detected PARP1, which was recently described to inhibit MICA expression on AML cells as part of the tumor immune evasion strategy which validates the approach." (PMID 37143070, 2023). "Mechanistically, these compounds enhanced the chemotaxis and cytotoxicity of γδ T cells through upregulating MICA/B and downregulating the levels of PD‐L1 and PD‐L2 on CAFs and tumour cells; while upregulating CXCR4, CD107a expression and IFN‐γ production in γδ T cells." (PMID 35731974, 2022). "Furthermore, hypoxia‐induced HIF‐1α can increase the expression of metalloproteinase ADAM10, which regulates the shedding of the MHC‐I‐chain related molecule A (MICA) from the tumour cell surface." (PMID 35466515, 2022). "However, several studies have observed that human tumor cells release soluble MICA by proteolytic shedding and that these sMICA molecules result in the downregulation of NKG2D and impede NKG2D-mediated tumor immune surveillance." (PMID 36119072, 2022). "Therefore, B2-OKT3 BiTE can target MICA on tumor cells and CD3ε on T cells through the tandem scFv BiTE format, which specifically induces T cells to kill tumor cells." (PMID 35401191, 2022). "The metastatic tumor model displayed a greater loss of stress ligands (ULBP1, MICA), downregulation of chemokine expression (MCP-1), and higher production of inhibitory soluble molecules (i.e., TGF-β, IL-6), as compared with a non-metastatic tumor model, more resembling the in vivo scenario." (PMID 35205760, 2022). "In this context, our data suggest that the modulation of MICA on tumor cells may be a potential limiting effect of GAS6/TAM inhibitors on immune surveillance." (PMID 35967396, 2022). "The immune activating molecule MICA belongs to a family of proteins, which are overexpressed on stressed cells such as tumour transformed or viral infected cells, and bind to the activating immune receptor NKG2D present on T lymphocytes and Natural Killer cells." (PMID 35135541, 2022). "The results showed that MICA/B were highly expressed in the tumor tissues." (PMID 35965586, 2022).
tumor (continued). "Interestingly, the expression of MICA/B was reported to be low on the surface of tumour cells, while elevated levels of soluble MICA/B were present in the sera of patients with different malignancies." (PMID 35806034, 2022). "In addition, hypoxia-induced shedding of MICA on the surface of pancreatic cancer cells enables tumor cells to evade NK cell immune killing." (PMID 36466812, 2022). "Similarly, treatment with histone deacetylase inhibitors, such as valproic acid, causes upregulation of the NKG2DL MICA/B and ULBP2 from the tumor cells." (PMID 35242135, 2022). "Notably, advanced tumor cells can utilize the proteolytic shedding of MICA/B to achieve immune escape." (PMID 36428748, 2022). "Further, transgenic mice expressing a shedding-resistant MICA avoided tumor progression." (PMID 36726591, 2022). "Therefore, antibody-mediated inhibition of MICA/B shedding promotes NK cell-driven anti-tumor immunity and has immunotherapeutic potential." (PMID 36555547, 2022). "ADAM10 and ADAM9 are sheddases that release MICA from the cell membrane of tumor cells." (PMID 36119072, 2022). "Next, we asked whether shedding of MICA/B was increased in the drug treatment groups at either time point, which can affect tumor recognition by NK cells." (PMID 34926577, 2021). "Interestingly, tumor cells are able to shed MICA and MICB from their surface, which can bind to the cell surface NKG2D and provokes an internalization of NKG2D into NK cells." (PMID 33800301, 2021). "In addition, matrix metalloprotease 14 (MMP14) promotes shedding of MHC class I Chain related molecule A (MICA), thus impairing NK and T cell anti-tumor responses." (PMID 34150958, 2021). "Additionally, the therapeutic efficacy of mAb-mediated neutralization of sMICA or MICA shedding has been shown to negatively affect tumor growth in mouse models." (PMID 34394116, 2021). "Also, 7C6 acts synergistically with the HDACi panobinostat through stabilizing tumor cell surface MICA/B expression and exhibits synergy with human cytokine-induced NK cells (CIK) in vitro." (PMID 34394116, 2021). "Among the mAb ligands, MICA was chosen as a target since it is most often expressed by tumor cells." (PMID 34835294, 2021). "Indeed, some ADAMs are expressed in malignant tumors and participate in cancer pathology with ADAM10 and ADAM17 playing a prominent role for this mechanism of tumor immune-evasion by controlling MICA and MICB." (PMID 33789714, 2021). "NKG2D ligands are members of the ULBP family and MICA/B, which are highly expressed on tumor cells." (PMID 34459571, 2021). "It was found that the highly expressed miR-20a in tumor cells can target the expression of MICA/B." (PMID 34084160, 2021). "Therefore, miR-20a targeting and silencing MICA/B can indirectly inhibit the cytotoxicity and tumor killing effects of NK cells." (PMID 34084160, 2021). "It is thus possible that changes in the expression patterns of lncRNAs like XXbac-BPG181B237 could contribute to the immune toleration of tumor cells by altering MICA presentation." (PMID 34943820, 2021). "In this sense, upregulation of tumor cell ligands MICA/B for activating NKG2D receptor, upregulation of adhesion CADM1 molecule, and downmodulation of E-cadherin ligand for inhibitory KLRG4 receptor, favor the elimination of tumor cell undergoing EMT by NK cells." (PMID 34858978, 2021). "Similarly, VPA enhanced NK92-mediated tumor control in a pancreatic-mouse model by upregulating MICA/B." (PMID 33572396, 2021). "Important membranous MICA/MICB staining was observed in tumor biopsies at various scores." (PMID 35967081, 2021). "Also, currently there is not a good estimate about the relative relevance of tumor cell surface-expressed MICA/B vs sMICA/B during tumor immunity." (PMID 34394116, 2021). "Therefore, several approaches are proposed to harness anti-tumor immunity via the targeting of MICA/B." (PMID 35967081, 2021).